CD4 (CD4 molecule)
Diseases named in the same sentence as CD4 in open-access papers (continued):
Sharing a sentence is not in itself a finding about the gene and the disease.
AIDS (continued). "HL is a frequent AIDS non-defining cancer; the probability of its occurrence can increase with moderate immunosuppression or with a high CD4 cell count." (PMID 34831094, 2021). "Overall, 73.7% did not progress to the WHO-AIDS stage, and 62.7% had a CD4 count above (±10%) of the baseline value (48.6% in Abidjan vs. 69.0% in Lomé, p < 0.001)." (PMID 34277512, 2021). "In the PASER-M cohort representing six countries in sub-Saharan Africa, among patients with VLS, those with poor CD4 recovery (<200) demonstrated significantly higher rates of HIV-related mortality, incidence of AIDS and incidence of pulmonary TB for several years post-ART initiation." (PMID 32584821, 2020). "In this study, the median CD4+ cell count in the ADE group was 29.00 cells/μL (IQR: 12.00–116.50), and 96.05% of patients with ADE had late presentation, demonstrating that most of patients with ADE were in an advanced stage of HIV/AIDS." (PMID 32680536, 2020). "Disseminated MAC (DMAC) infections usually occur in patients in advanced stages of HIV/AIDS when blood CD4+ T cell counts are lower than 50/mm3, unlike M. tuberculosis that can infect patients at any stage of AIDS." (PMID 32781595, 2020). "Based on a retrospective observational cohort of children with HIV infected from the Guangxi Center for Disease Prevention and Control (CDC), the variables of all patients included viral loads, CD4 counts, laboratory results and WHO clinical staging of HIV/AIDS were collected." (PMID 32210333, 2020). "IFI16 detects abortive HIV-1 reverse transcripts in CD4 T cells, leading to pyroptosis; however, rather than protecting the host, this mechanism depletes CD4 T cells and contributes to progression to AIDS." (PMID 32751803, 2020). "Independent risk factors for death included: being urban residents, nadir CD4+ T-cell count being <200 cells/μL, not being on cART, and having comorbidities such as Pneumocystis pneumonia, hepatitis C, talaromycosis, non-AIDS malignancy, and kidney disease." (PMID 33681235, 2020). "Patients who were diagnosed with AIDS as the first event tended to be younger, have more prevalence in 1984–85 and 1987–90 recruitments, lower CD4, higher CD8, and higher RBC in comparison with patients who were diagnosed with non-AIDS diseases as the first event." (PMID 31996148, 2020). "Long-term nonprogressor (LTNP) cases comprise an HIV-1 infection group that does not follow the normal course of AIDS progression due to the ability to spontaneously maintain high levels of CD4+ T cells and a low viral load in the absence of therapy." (PMID 32711474, 2020). "Our cohort included six AIDS patients; however, we did not observe an over-representation of X4 viruses in our AIDS patients (CD4 counts < 200 cells/μL, p = 0.92)." (PMID 32678115, 2020). "Thus, in the present study, we measured the P. jirovecii infection rate among HIV-positive and AIDS (HIV/AIDS) patients with suspected PCP and investigated the relationship between CD4+ T cell count and PCP occurrence." (PMID 32911508, 2020). "In prior studies, higher attrition has been observed among PLWH with indicators of asymptomatic disease, such as high CD4 counts or no AIDS‐defining diagnosis." (PMID 33000914, 2020). "Despite increased focus on testing and linkage to care in recent years, across Europe, an estimated 40–60% of people do not present for HIV care until their CD4 cell count has decreased below 350 cells/mm3 or they have experienced an AIDS defining disease." (PMID 33028235, 2020). "This is due to the fact that as the current CD4 count raises, the duration on ART increases and the VL is suppressed; HIV/AIDS-related mortality might also decline." (PMID 32838734, 2020). "Inclusion of both CD4 cell count based disease progression states and viral load, in the time-homogeneous Markov model, assisted in modeling the complete disease progression of HIV/AIDS." (PMID 32228523, 2020).
AIDS (continued). "The CD4 criteria for ART initiation was further modified in 2009 to ≤ 250 cells/mm3 and to ≤ 350 cells/mm3 in 2012, as recommended by the Joint United Nations Programme on HIV/AIDS (UNAIDS)." (PMID 32257156, 2020). "A previous clinical diagnosis of AIDS, a lower CD4+ nadir, drug abuse or current smoking were not related, in our analysis, to eGFR reduction." (PMID 33057418, 2020). "Despite these animals being infected with SIV, with high levels of viral replication and depletion of gut CD4+ T cells, sooty mangabeys do not progress to AIDS." (PMID 33178456, 2020). "Late presentation is defined well as, a patient diagnosed with the first CD4+ cell count < 350/μL, or a patient with AIDS-defining illness regardless of CD4+ cell count during diagnosis." (PMID 32680536, 2020). "Similarly, very few of the studies have evaluated the level of immune markers such as CD8 counts and the CD4/CD8 ratio, which has been considered a prognostic parameter of non-AIDS morbidity." (PMID 33294453, 2020). "Although the main markers of HIV disease progression are both viral load and CD4 count, relatively few HIV/AIDS disease progression modelling studies include the longitudinal measurements of viral load biomarker along with clinical states of HIV/AIDS disease progression." (PMID 32228523, 2020). "Collectively, the results presented so far raise the prospect that, if the ability of non-CD4 cells to invoke inflammasome-dependent, IL18-driven production of IFN-γ can be enhanced, it may be possible to control acute toxoplasmosis in AIDS." (PMID 32753607, 2020). "The PD-1 expression level in intestinal mucosa of HIV/AIDS patients was significantly negative correlated with the number of CD4 + T cells (rs = − 0.238, p = 0.016)." (PMID 32891157, 2020). "Herpes zoster often occurs early in HIV infection and is not considered as AIDS-defining conditions; in contrast, cryptococcal meningitis is common in patients with advanced stages having very low CD4 counts." (PMID 32963654, 2020). "The reduction of CD4 count and presence of opportunistic infections in the later stages of HIV/AIDS may explain why patients may have additional fatigue intensity." (PMID 32295546, 2020). "Persistent oropharyngeal candidiasis and Esophageal candidiasis (OC) or candidiasis of the trachea, bronchi, or lungs are common AIDS-defining lesions seen in PLHIV in World Health Organization (WHO) clinical stages III and IV or CD4 T lymphocyte cell count < 200 cells/mm3." (PMID 32982560, 2020). "Therefore CD4 count, VL, age, WHO AIDS stages, gender and residence should be utilised in solving health care challenges associated with elderly PLWHA." (PMID 34394214, 2020). "The portability of the BD FACSPresto system and its ability to accurately measure three critical parameters (AbsCD4, CD4%, and Hb levels) that reflect the clinical status of people living with HIV/AIDS makes it well-suited for use as a point-of-care CD4 testing technology." (PMID 33177659, 2020). "As a natural host for HIV-1, chimpanzees (Pan troglodytes) can be infected with HIV-1, but they neither develop AIDS, nor permanently lose their CD4+ T cells." (PMID 31824943, 2019). "On the other hand, the levels of CD4 and the time of AIDS were the same in coinfected patients, independent of the presence of the GPG or GWG motif." (PMID 31335686, 2019). "However, there is paucity of studies investigating the relationship between intestinal parasitic infections with CD4 counts and anemia in HIV/AIDS patients starting Antiretroviral Therapy (ART) in this region particularly and in Ethiopia in general." (PMID 31029088, 2019). "Factors such as social support, self-efficacy, income level, and high CD4 count have a protective effect on the QOL in young HIV-infected MSM, whereas discrimination, AIDS stage, and high-risk behaviors have a negative effect on QOL." (PMID 31349674, 2019).
AIDS (continued). "AIDS in HIV patients is defined by a CD4+ cell count <200 cells/mm3 or by the presence of an AIDS-defining illness, regardless of CD4 cell levels." (PMID 31905656, 2019). "We demonstrated in a SIV-infected macaque model of AIDS and suppressive ART that the frequency of latently infected resting CD4 T cells in blood and lymph nodes was one infected cell per million CD4 T cells, which is the same frequency observed in ART-suppressed HIV-infected individuals." (PMID 31431552, 2019). "CD4 count was obtained in 64.7% (112/173) of patients, with median value of 87 cells/μL (IQR 25–266), and was further staged as severe immunosuppression: CD4 < 100 cells/μL (50%, 56/112); AIDS: CD4 < 200 cells/μL (69.6%, 78/112); and late-stage HIV disease: CD4 < 350 cells/μL (83%, 93/112)." (PMID 31638941, 2019). "Rates of new AIDS-defining illness or death at 48 weeks, according to CD4+ T-cell count restricted on non-attritors." (PMID 30707696, 2019). "We included a total of 3171 patients with CD4 ≥350 cells/mm3 and no AIDS defining event at enrolment." (PMID 31855320, 2019). "In fact, late diagnosis of HIV infection, defined as an initial CD4+ T lymphocyte count < 200 cells/μl, among newly identified HIV/AIDS cases in China is a challenge for HIV control and prevention, which is detrimental to infected persons and to the public health." (PMID 31711447, 2019). "Clinical studies indicate that female gender is associated with lower viral loads, higher CD4 counts, pronounced ART side effects, and a more rapid progression to AIDS, though this has not been shown in the Yunnan population." (PMID 30998710, 2019). "At the time of starting ART, median age was 37 years (IQR 31–45), median CD4+ count was 252 cells/μl (IQR 126–377), median HIV-1 viral load was 63 160 (IQR 11 900–199 800) copies/ml and 17 127 (18.2%) PLHIV had been diagnosed with AIDS." (PMID 31800404, 2019). "The ECDC HIV Modelling Tool takes missing data into account by assuming that CD4+ count data are missing at random in individuals with no concurrent AIDS diagnosis." (PMID 30968824, 2019). "“Treat All” – the treatment of all people with HIV, irrespective of disease stage or CD4 cell count – represents a paradigm shift in HIV care that has the potential to end AIDS as a public health threat." (PMID 30657644, 2019). "These associations persisted, and, in the case of sCD163 and CRP, increased in magnitude (aOR = 3.39, p = 0.01 and aOR = 2.26, p = 0.04, respectively), after additional adjustment for CD4, CD4 nadir, use of HAART, history of AIDS diagnosis, and 5-year HIV viral suppression." (PMID 30946765, 2019). "At treatment initiation, median age was 36 years (interquartile range [IQR]: 30–44), median CD4+ T-cell count was 416 cells/μL (IQR: 243–591), 8.5% of patients had a history of AIDS diagnosis, 34.5% had a viral load >100,000 copies/mL and 89.2% were attending hospitals with more than 500 beds." (PMID 31449566, 2019). "All cART‐naive individuals ≥18 years of age from 2003 to 2017 with CD4 ≥350 cells/mm3 and without AIDS at enrolment at five CCASAnet sites (Brazil, Chile, Honduras, Mexico and Peru) were included." (PMID 31855320, 2019). "Antiretroviral therapy should be initiated as soon as possible in patients diagnosed with AIDS, regardless of the CD4+ cell count, as the delayed initiation of cART has been shown to significantly increase the risk of developing ARL30." (PMID 30926889, 2019). "In a study done amongst Ugandan AIDS patients without cryptococcosis, the mortality rate was much lower at 3.68 and 2.75 per 100 person-years among groups with CD4 between 50–99 and 100–149 cells/uL respectively." (PMID 30699151, 2019). "AIDS‐KS patients in trend with the screening, with RQ < 1, had significantly lower CD4 levels compared to AIDS‐KS patients not in trend, with RQ > 1, both at baseline (P = 0.0230) and after treatment (P = 0.0140) (and data not shown)." (PMID 30549196, 2019).
AIDS (continued). "The current study aimed at measuring and evaluating the impact of soluble Fas receptors and ligands in HIV/AIDS infected and exposed non-infected children and the correlation with CD4+ cell depletion and HIV-1 RNA load in the sub-group of those infected." (PMID 31762906, 2019). "When all the other covariates were included in the mode (i.e., age, education, relationship status, CD4 count, duration of being diagnosed with HIV infection, duration of antiretroviral therapy and being in the AIDS stage) for HRQoL, trajectories of gender remained insignificant." (PMID 31396129, 2019). "Limited access to HIV testing, cART centers, and CD4 counts were previously highlighted as a barrier to timely initiation of cART, particularly in ambulatory HIV/AIDS care settings, and indeed increased availability of these services has increased cART initiation rates." (PMID 31057959, 2019). "Our Helios CD4 analyzer would enable CD4 test results to be rapidly obtained using a drop of blood in a POC setting, which can greatly decrease the time delay from diagnosis to initiation of the ART and thus reduce mortality from HIV/AIDS." (PMID 30875995, 2019). "At the time of diagnosis, 62.0% of participants had not yet progressed to AIDS, while 38% had, and baseline CD4 counts were low—25.6% had ≥350 cells/mm3, 22.1% had 200–399 cells/mm3, and 27.2% had <200 cells/mm3." (PMID 31344059, 2019). "In 2016, the estimated coverage of ART services was 48% and the country adapted the WHO Guideline on Universal Treatment Access for patients with HIV/AIDS, which showed that all HIV-infected patients can start having ART as soon as possible with any CD4 cell count and at any clinical stage." (PMID 30562949, 2018). "Also in this study, and in accordance with WHO clinical staging of HIV/AIDS at baseline, about 57% of participants had progressed to stage III (CD4 count < 200 cells/μL) with 33% at stage II (200–499 cells/mL)." (PMID 29850480, 2018). "In the present study, the CD4 count and WHO stage were used to indicate HIV/AIDS progression." (PMID 29736152, 2018). "Patients with VF were 69.6% males, mean age 45 (IQR 38 to 51) years, Caucasians 85.7%, with time of known HIV infection 15 (IQR 10 to 19) years, 45.5% sexual acquisition, nadir CD4 97 cells/mm3 and 69.1% AIDS stage, without finding differences between INSTI." (PMID 30362663, 2018). "By univariable analysis, factors associated with overall five-year mortality were age, AIDS status, non-HIV related cancer, cardiovascular disease, decreased eGFR, cirrhosis, anemia, low BMI, CD4 cell count, CD4 nadir, and detectable HIV viral load." (PMID 29672628, 2018). "Patients with PSH had a higher proportion of subjects with CD4 <350 cells/ml (91.6% vs. 83.4%, p < 0.001), fewer patients receiving ART (50.8% vs. 59.9%, p = 0.003), and were more frequently hospitalized due to AIDS‐related events (80.0% vs. 69.3%, p=< 0.001) in comparison with regular stay." (PMID 29671462, 2018). "For the HIV → AIDS transition, patients with the CD4 count smaller than 200 and not using HAART have the worst survival." (PMID 30424736, 2018). "CD4 T-cell count is a reliable predictor of host immune status, with counts of <500 indicating immune suppression, and counts of <200 in HIV-infected individuals indicating AIDS." (PMID 30352938, 2018). "Accordingly, the WHO and Joint United Nation program on HIV/AIDS (UNAIDS) have recommended CPT for HIV/AIDS patients in Africa with symptomatic HIV diseases (WHO clinical stage 3 or 4) and individuals who have a CD4 count of less than or equal to 350 cells/mm3." (PMID 30042677, 2018). "To date, progression to AIDS (CD4 < 200) has not been observed in an HLA-B*27:05-positive subject without escape occurring in this epitope." (PMID 29167337, 2018). "cART should begin in all HIV-infected patients, regardless of the CD4+ T-cells count in order to decrease the risk of HIV transmission and prevent AIDS-related illness." (PMID 30522500, 2018).
AIDS (continued). "Although the alterations were more intense for VL/HIV-AIDS patients than for TL/HIV-AIDS ones, the authors observed lower CD4+ T cell counts and higher proportion of activated T lymphocytes in co-infected patients even when HIV viral load was suppressed under HAART." (PMID 29971054, 2018). "Late presenters were defined as persons with initial CD4 count between 200 and 350 cells/μL; those with advanced disease had an initial CD4 count <200 cells/μL or clinical AIDS regardless of CD4 count." (PMID 30362663, 2018). "The remainder were observational studies with a variety of outcomes, including mortality, progression to AIDS, progression to AIDS or death, serious non-AIDS events, CD4+ T-cell counts increase, virologic suppression, and virologic failure." (PMID 29487595, 2018). "Both CD8+ and CD4+ T cells can be involved in delayed progression to AIDS and suppression of viral replication in the absence of ART." (PMID 30534128, 2018). "In advanced HIV/AIDS (stage III or IV) and/or in cases of severe reduction in CD4 count, nevirapine based ART regimen may be initiated for better immune recovery." (PMID 30042677, 2018). "The presence of AIDS, opportunistic infection and both T CD4 counts and viral load did not alter Ficolin-1 levels in HIV infected or coinfected patients." (PMID 30349535, 2018). "Our results suggest that 16% of AIDS and non-AIDS events could be averted as a result of new recommendations for earlier ART initiation, compared to prior recommendations of delaying ART until lower CD4 thresholds." (PMID 30395635, 2018). "The Dat’AIDS score comprises simple and reliable predictors such as age, CD4 cell count, history of non-HIV related cancer, history of cardiovascular disease, eGFR, cirrhosis, BMI and anemia, which are all easily obtainable at assessment." (PMID 29672628, 2018). "Advanced Late presentation is presentation for care with a CD4+ T cell count below 200 cells/mm3, or presenting with an AIDS-defining event, regardless of the CD4+ T cell count." (PMID 29970017, 2018). "CD4+ T cells are also the primary target for infection with the human immunodeficiency virus type 1 (HIV-1), and their depletion heralds the onset of acquired immunodeficiency syndrome (AIDS)." (PMID 29518929, 2018). "In conclusion, more studies are required to determine the prevalence of HTLV-1 and its impact on CD4 lymphocyte counts (both absolute and relative), HIV viral load and AIDS progression in co-infected individuals in sub-Saharan Africa and other regions with a high HIV burden." (PMID 30344845, 2018). "According to the definition approved by the European Consensus panel, Late Presenters are defined as patients, who are in need of care, with a CD4+ T-cell count below 350 cells/μl or with an AIDS-defining event regardless of the CD4+ T-cell count." (PMID 30587143, 2018). "Late presentation was defined as persons presenting for care with a CD4+ T cell count below 350 cells/mm3 or presenting with an AIDS-defining event, regardless of the CD4 cell count." (PMID 29970017, 2018). "Evolution to AIDS greater than a year, not receiving HAART, weight loss, hypoalbuminemia, Karnofsky score, CD4 count, MV, RI, LF and APACHE II score ≥13 were significantly associated with mortality." (PMID 29671462, 2018). "For example, the authors did not consider respondents’ HIV/AIDS stage and clinical conditions including CD4 count." (PMID 30026946, 2018). "Thus, most patients have elevated CD4+ T-cells count, stable CD4+ T-cell trajectories, and more favorable clinical outcomes compared with viremic patients; but a subgroup of HIV-ECs may progress to AIDS with CD4+ T-cells decline and/or loss of virologic control." (PMID 29967620, 2018). "Where persistence of CD4:CD8 ratio abnormality was observed, on-going immune activation may have significance for non-AIDS outcomes." (PMID 29465561, 2018).